CTLA4 (cytotoxic T-lymphocyte associated protein 4)
Diseases named in the same sentence as CTLA4 in open-access papers (continued):
Sharing a sentence is not in itself a finding about the gene and the disease.
colitis (continued). "The incidence of serious immune-related adverse events (irAE) associated with immune checkpoint blockade such as colitis or rash is approximately 20% for nivolumab or pembrolizumab (anti-PD-1) treated patients and 28% in ipilimumab (anti-CTLA4)-treated patients." (PMID 33127658, 2020). "However, when we treated the mice with the anti-CTLA-4 antibody, the trafficking blockade group developed more severe colitis than the control group, showing more dramatic weight loss and a lower survival rate." (PMID 32183814, 2020). "The higher abundance of members from the phylum Bacteroidetes was also associated with protection from anti-CTLA-4-induced colitis, further confirming the benefits that these bacteria could have in anti-CTLA-4 antibody therapy." (PMID 31294239, 2018). "In all, these analytical models identify bacterial pathways that may confer resistance to colitis and serve as biomarkers for patients at high risk of developing CTLA-4 blockade-induced colitis." (PMID 26837003, 2016). "Colitis is also among the most frequent and problematic immune-mediated adverse events that are associated with dual checkpoint inhibition and a combination of anti-CTLA4 and anti-PD-1 monoclonal antibodies has been shown to exacerbate dextran sulfate sodium-induced autoimmune colitis in mice." (PMID 39404738, 2025). "Among them all, CTLA4-inhibitors and, in particular, ipilimumab, are more frequently associated with colitis; this finding could be explained by the fact that the pathway induced by CTLA-4 is dependent on antigen-presenting cells; therefore, it is upstream compared to the PD1-PD-L1 signal." (PMID 37239166, 2023). "Furthermore, the polyamine transport deficiencies associated with the increased risk of cytotoxic T cell antigen 4 (CTLA-4) blockade-induced colitis may be caused by this disruption to the ecological network balance in the gastrointestinal tract." (PMID 35743481, 2022). "One underlying reason may be incomplete records in the electronic medical system and more patients receiving CTLA-4 inhibitor in clinical trials, as CTLA-4 inhibitors are associated with an increased risk of colitis and hepatitis compared to PD-1/PD-L1 inhibitors." (PMID 36438818, 2022). "Notably, there are two types of anti-CTLA-4 associated colitis reported in the literature." (PMID 34221257, 2021). "Additionally, colitis may be caused by autoimmune-related mechanisms during treatment with CTLA4 blockade." (PMID 34094935, 2021). "Furthermore, the anti-CTLA-4 mAb has been previously reported to exert marked therapeutic effects against various cancers and worm infections, but causes obvious body damage, i.e., immune-related adverse events, including colitis, hepatitis, and pneumonitis." (PMID 31134084, 2019). "Identification of biomarkers that predict the risk of developing colitis may help identify patients that are particularly susceptible to distinct forms of immunotherapy-induced inflammation, such as with CTLA-4 blockade, and may facilitate preemptive treatments." (PMID 26837003, 2016). "In addition, we show that the presence of microbiota-associated modules for bacterial polyamine transport system and the biosynthesis of thiamine, riboflavin and pantothenate can accurately assess a patient's risk of developing colitis following CTLA-4 blockade." (PMID 26837003, 2016). "In mice experiencing colitis‐related adverse reactions following anti‐CTLA‐4 treatment, supplementation with Bifidobacterium significantly ameliorates colitis symptoms in mice with ATB‐disrupted gut microbiome." (PMID 41574027, 2026). "Fecal microbiome transplantation from a patient with ir-colitis into mice induced surrogate markers of colonic inflammation and enhanced the anti-tumor activity of combined anti-PD-1/CTLA-4." (PMID 42083059, 2026).
colitis (continued). "Their findings revealed that all-grade colitis (OR 8.7, 95 % CI 5.8–12.9), hypophysitis (OR 6.5, 95 % CI 3.0–14.3) and rash (OR 2.0, 95 % CI 1.8–2.3) were more prevalent with CTLA-4 monoclonal antibodies." (PMID 39866435, 2025). "Bacteroides fragilis, thetaiotaomicron on fecal transplant into germ-free mice restored CTLA-4 blockade efficacy, reduced colitis, and showed higher fecal abundance of B. fragilis (P < 0.01) that inversely correlated with tumor size after treatment." (PMID 41472726, 2025). "Colitis represents the predominant adverse reaction to anti-CTLA-4 immune checkpoint therapy, where biomarkers to forecast severe diarrhoea associated with this treatment are still lacking." (PMID 39759851, 2025). "Clinical studies have demonstrated that Cadonilimab exhibits a favorable safety profile, particularly showing a marked reduction in high-grade irAEs, such as colitis and hypophysitis, compared to conventional CTLA-4 inhibitors." (PMID 40777022, 2025). "Based on prior studies, the incidence of colitis of any grade ranged from 5.7% to 39.1% for CTLA-4 inhibitors and from 0.7% to 31.6% for PD-1/PD-L1 inhibitors." (PMID 40465755, 2025). "Administration of checkpoint inhibitors such as anti-CTLA-4 mAb induces severe colitis in a subset of cancer patients undergoing treatment with this immunotherapeutic antibody." (PMID 40019007, 2025). "Mechanistically, a 6.3‐fold increase in PD1/CTLA‐4 BsAb accumulation in tumors due to the tumor targeting ability of aPD1, and the PD1/CTLA‐4 BsAb significantly reduces the adverse colitis event in healthy mice, compared to aPD1 and aCTLA‐4." (PMID 39606809, 2025). "Colitis induced by immune checkpoint inhibitors (ICIs), including anti-CTLA-4 and PD-1/PD-L1 antibodies, exhibits unique immunological characteristics." (PMID 40457634, 2025). "Common AEs reported with CTLA-4 inhibitors include colitis, hypophysitis, and rash, while pneumonia and hypothyroidism are common in patients using PD-1 inhibitors." (PMID 41459523, 2025). "Supporting evidence comes from a smaller study (n=13) reporting substantially higher colitis incidence with anti-CTLA4 versus PD1 inhibitors (9.1% vs 1.6%)." (PMID 41341585, 2025). "The median onset of diarrhea/colitis typically occurs around 3 to 6 months after treatment with anti-PD-1/Programmed cell death-ligand 1 (PD-L1) agents, while earlier for anti-CTLA-4 agents at around 6 to 8 weeks." (PMID 40165945, 2025). "This contrasts with anti-CTLA-4 agents (e.g., ipilimumab), which show weaker hepatitis signals but higher propensity for other irAEs (e.g., colitis)." (PMID 41221037, 2025). "This is consistent with previous studies reporting higher rates of colitis and diarrhea with CTLA-4 blockade, likely due to enhanced T-cell activation and reduced regulatory T-cell (Treg) function in the gut mucosa." (PMID 40867263, 2025). "Our analysis confirmed that colitis is a dominant digestive irAE, with ipilimumab (anti-CTLA-4) exhibiting significantly stronger signal intensities for colitis compared to anti-PD-1/PD-L1 agents—consistent with previous systematic reviews." (PMID 41221037, 2025). "The incidence of colitis is 3.4–22% with CTLA-4 inhibitor therapy, 0.7–12.8% with combined CTLA-4 and PD-1 inhibitor therapy, and 0.7–2.6% with PD-1/PD-L1 inhibitor monotherapy." (PMID 39064558, 2024). "Anti-IL-6 combined with antibiotics increased the efficacy of anti-CTLA-4 and reduced colitis severity in Stat3Δ/Δ mice." (PMID 39247203, 2024). "We analyzed BCs and the occurrence of severe colitis, hepatitis, and pneumonitis in 22 treatment arms and 3 treatment groups: anti-CTLA-4 (n = 2904), anti-PD-1 (n = 1301), or combination therapy (n = 822)." (PMID 38254742, 2024). "This research opens up novel avenues for employing anti‐CTLA‐4 antibody therapy to circumvent the onset of colitis, which is often considered the Achilles' heel of what is arguably the most efficacious treatment for certain blood cancers and/or solid tumors." (PMID 38881673, 2024).
colitis (continued). "Genetic deletion or antibody blockade of CTLA-4 in multiple in vivo models of colitis demonstrates that this pathway plays a key role in intestinal homeostasis." (PMID 39496592, 2024). "Dermatologic events, colitis, and hepatitis are more frequent with CTLA-4 inhibitors, while pneumonitis, thyroid dysfunction, and rheumatologic issues are more common with PD-1/PD-L1 inhibitors." (PMID 38791974, 2024). "Colitis, the most frequent serious irAE previously reported with anti-CTLA4 therapy, was seen in both syndromes." (PMID 37823831, 2024). "CTLA‐4‐targeting monoclonal antibodies (MoAbs) activate the T cells in the gut, leading to colitis characterised by elevated CD4+ effector and regulatory T cells (Tregs), accompanied by significant changes in Treg gene expression." (PMID 38451000, 2024). "In recent years, blockade of immune checkpoints, in particular CTLA-4 and PD-1, has been found to cause a form of IBD, CPI-induced colitis (CPI-C)." (PMID 39496592, 2024). "In fact, blockade of IL-6 was found to not only ameliorate colitis-irAE but also enhance the antitumor efficacy of anti-CTLA-4 therapy in mouse models and patient cohorts." (PMID 39247203, 2024). "Checkpoint inhibitors, particularly those targeting the CTLA-4 pathway, disrupt this fine balance and can lead to inflammatory bowel disease and immune checkpoint colitis." (PMID 39496592, 2024). "Conversely, certain Firmicutes species can exacerbate colitis, a common side effect of anti-CTLA-4 treatment." (PMID 39408584, 2024). "Taken together, multiple colitis models show that CTLA-4 expressing ILCs play a role in regulating inflammation in the colon." (PMID 39496592, 2024). "This study provides insight into the regulation of CTLA-4 in ILCs, and how blockade or genetic deletion of this crucial regulatory molecule leads to exacerbated disease in mouse models of colitis and in patients with conventional IBD and CPI-C." (PMID 39496592, 2024). "A recent study shows that CTLA‐4 blockade‐induced colitis in mice is dependent on the composition of their intestinal microbiota." (PMID 39031507, 2024). "Ctla4 was the most highly upregulated checkpoint gene in all the colitis models, with less pronounced changes in the expression of Pdcd1, Lag3, Vsir and Havcr2." (PMID 39496592, 2024). "Although colitis and diarrhea have been recorded, PD-1 antibody therapy has fewer side effects than CTLA-4 antibody therapy." (PMID 38564002, 2024). "In a mouse model, combining anti-CTLA-4 treatment with dextran sulfate sodium induced severe colitis." (PMID 39408584, 2024). "Immune checkpoint blockade (ICB)‐induced colitis represents one of the most frequent and severe irAEs among patients treated with anti‐CTLA‐4 antibodies, either alone or in combination with anti‐PD‐1 antibodies." (PMID 38881673, 2024). "Here, we show that CTLA-4 plays an important role in restraining innate immune activation in the colon in multiple colitis models." (PMID 39496592, 2024). "Specific gut bacterial strains protect against anti-CTLA-4 colitis in mice, and in humans, a high abundance of Bacteroides is linked to a lower incidence of colitis." (PMID 39682118, 2024). "Patients with ICI colitis who underwent combined anti-CTLA4 and anti-PD1 therapy exhibited an enrichment of bone marrow-derived cells, notably inflammatory DCs, alongside a reduction in CD4+ tissue-resident memory T cells." (PMID 39456702, 2024). "When PD-1/PD-L1 inhibitors and CTLA-4 inhibitors are combined, the reported incidence and severity of colitis tend to be higher." (PMID 39451777, 2024). "Likelihood of recurrence of colitis is higher with CTLA-4 inhibitor therapy or dual (CTLA-4 inhibitor + PD-1/PD-L1 inhibitor) therapy, and therefore CTLA-4 inhibitor therapy is advised against after severe colitis has subsided." (PMID 38517981, 2024). "CTLA-4 inhibitors frequently lead to colitis, hypophysitis, and rash, while PD-1/PD-L1 inhibitors are more commonly associated with pneumonitis, colitis, and thyroiditis." (PMID 39684531, 2024).
colitis (continued). "The incidence rates of colitis with CTLA-4 inhibitors and PD-1 inhibitors are 27-54% and 19.2%, respectively." (PMID 38410506, 2024). "The reported incidence rates of colitis with CTLA-4 inhibitors and PD-1 inhibitors are approximately 27-54% and 19.2%, respectively." (PMID 38410506, 2024). "The spectrum varied significantly by regimen: of 193 anti-CTLA-4 deaths, 70% (135 cases) were attributed to colitis." (PMID 39456702, 2024). "With CTLA-4-inhibitor therapy, colitis, hepatitis, and pneumonitis are predominant, and in anti-PD-1/PD-L1 regimens, pneumonitis, hepatitis, colitis, neurological events, and myocarditis are relatively common." (PMID 38136332, 2023). "Specifically, the increase of CD4+ T lymphocytes is usually found in subjects treated with anti-CTLA-4, while the increase of CD8+ is associated with anti-PD-1 colitis." (PMID 37511260, 2023). "For combined anti-PD-1/anti-PD-L1 and anti-CTLA-4 treatment, the most common fatal irAEs were colitis (37%) and myocarditis (25%)." (PMID 36600271, 2023). "Diarrhea and colitis occur in 10%-35% of patients treated with anti-CTLA-4, 1%-10% with anti-PD-1, and 15-32% with anti-PD-1 and anti-CTLA-4 combination therapy." (PMID 37251665, 2023). "An increase in serum IL-17 levels was demonstrated following CTLA-4 blockade with ipilimumab in patients developing colitis, consistent with CTLA-4 inhibiting the production of IL-17 by type 17 T helper (Th17) cells." (PMID 36900420, 2023). "For example, death from colon inflammation is more frequent in patients receiving anti-CTLA-4 drugs, while death from lung inflammation occurs more in patients receiving anti-PD-1 or anti-PD-L1 drugs." (PMID 37445336, 2023). "Previous studies have reported the median time duration of developing ICI-induced colitis was 80~110 days with shorter duration for CTLA-4 inhibitors than PD-1/L1 inhibitors in Western population, which was in accordance with our study." (PMID 38090496, 2023). "A recurrence in ICI colitis was seen in 32% of patients who recommenced anti-PD-1/L1 therapy and in 44% of patients who recommenced anti-CTLA-4 therapy, and recurrence was typically observed earlier in onset." (PMID 36765649, 2023). "Molecular profiling of the colon following induction of colitis with either anti-CTLA4 or anti-PD-1 monotherapy was performed using RNA-seq." (PMID 37872166, 2023). "Gastrointestinal irAEs are more frequent and more severe in patients who receive CTLA-4 inhibitors than in those who receive PD-1 inhibitors, with rates of diarrhea ranging from 27% to 54% and colitis ranging from 8% to 22%." (PMID 37304306, 2023). "Although rare (0.3–1.3%), fatal adverse events related to ICIs are mostly represented by colitis and toxic megacolon with colonic perforation, especially with anti-CTLA-4." (PMID 37511260, 2023). "In agreement with our findings, we observed increased expression of IFNG, GZMB CXCR6 and CTLA4 in T cell clusters in with patients with CPI colitis patients in comparison with healthy controls." (PMID 37872166, 2023). "Out of these, 198 deaths were due to anti-CTLA-4 therapy, and ICI colitis was the cause in 135 cases (70%)." (PMID 36765649, 2023). "Pooled meta-analysis data suggest that diarrhea (13% vs. 33%) and colitis (1.4% vs. 9.1%) are less frequent with PD-1/PD-L1 inhibitors compared to CTLA-4 therapy, but symptoms persist longer (2 months vs. 1.4 months)." (PMID 36769093, 2023). "Other studies have indicated a possible remedial role of probiotic strains of bacteria, such as Bifidobacteria and Lactobacillus, in murine models of DSS colitis with the presence of an anti-CTLA4 blockade antibody." (PMID 37872166, 2023). "Data from our preclinical model support this notion, with mice receiving CTLA4 blockade experiencing more severe colitis than mice treated with anti-PD-1 alone." (PMID 37872166, 2023).
colitis (continued). "Ipilimumab inhibits regulatory T-cells (Tregs) as an effect of the high expression of CTLA4, and in parallel, increases the activity of effector T cells resulting in tumor response as well as colitis." (PMID 37239166, 2023). "For instance, colitis seems most frequent with anti-CTLA-4 and pneumonitis with anti-P-D1/PD-L1 antibodies." (PMID 36765845, 2023). "Of the Bifidobacterium mixture, B. breve specifically ameliorates CTLA-4 blockade-induced colitis, also via enhanced Treg function." (PMID 38055306, 2023). "A meta-analysis reported that the incidence of grade 3~4 colitis was 9.1% with CTLA-4 monotherapy, 1.3% with PD-1/L1 therapy, and 13.6% with combination therapy." (PMID 38090496, 2023). "Colitis and hypophysitis were seen more often with CTLA-4 inhibitors, while hypothyroidism, hyperthyroidism, and pneumonitis were more common in PD-1 inhibitors." (PMID 37342323, 2023). "This altered commensal community enhanced the IL-10–mediated inhibitory function of intestinal Tregs, which contributed to the mitigation of colitis in mice in the context of CTLA-4 blockade." (PMID 37404814, 2023). "ICI colitis is the most frequent irAE with anti-CTLA-4 or anti-PD-1+anti-CTLA-4 (combination ICI) therapy, and can present with the first ICI treatment or as late as greater than 4 mo after completing therapy." (PMID 36622383, 2023). "Rikenellaceae, which belongs to the Bacteroidetes phylum, is correlated with resistance to CTLA-4 inhibitor-related colitis, and a reduction in butyrate-producing taxa promotes systemic inflammation and atherosclerosis." (PMID 34980222, 2022). "Data from some clinical trials also shows less organ-toxicity such as pneumonitis and colitis in patients receiving PD-L1 inhibitors than PD-1 and CTLA-4 inhibitors." (PMID 37674988, 2022). "The incidence of irAE colitis is reported to be 0.7–1.6% with anti-PD-1 therapy, 5.7–9.1% with anti-CTLA-4 therapy, and nearly 13.6% with the combination of anti-PD-1/PD-L1 and anti-CTLA-4 therapies." (PMID 35740355, 2022). "Colitis, rash, and hypophysitis are the most frequent adverse effects of CTLA4 inhibitors, whereas arthralgia, pneumonitis, vitiligo, and hypothyroidism are most frequent with PD-L1 inhibitors, with high temporal unpredictability." (PMID 35774996, 2022). "Colitis, hypophysitis and rash are more common with anti-CTLA-4 therapy, while pneumonitis, hypothyroidism, musculoskeletal toxicities and vitiligo occurred more often with anti-PD-1 therapy." (PMID 36564402, 2022). "Of the two patients who had a pathogenic mutation in CTLA4, one had an IBD-like colitis (# 7); the other one had a lymphocytic-colitis-like histology (# 6)." (PMID 34599484, 2022). "Several subjects experienced severe immune-related toxicities consistent with known class effects of anti-CTLA-4 therapy, which included diarrhea, colitis, and rash." (PMID 35440655, 2022). "Colitis and hypophysitis occur more frequently with anti-CTLA-4 therapy, whereas pneumonitis and thyroiditis appear to be more common with anti-PD-1 therapy." (PMID 35015209, 2022). "It has been demonstrated that in mice with CTLA-4-induced colitis, administration of Bifidobacterium resulted in significantly less weight loss without compromising the therapeutic efficacy of ICI18." (PMID 35046403, 2022). "A systematic review found that colitis more commonly occurs with CTLA-4 inhibitors compared to PDL-1 inhibitors (OR:8.7, 95%CI: 5.8.12.9)." (PMID 35160275, 2022). "CTLA-4 inhibitors are prone to colitis, while PD-1/PD-L1 inhibitors have a high incidence rate of pneumonia and thyroiditis." (PMID 36189293, 2022). "Factors associated with a higher rate of irAE recurrence were the use of anti-CTLA-4 at rechallenge and the type of the irAE (colitis, hepatitis, and pneumonitis), but only few of our patients were concerned by these situations." (PMID 35222642, 2022).